RPS28P7 (ribosomal protein S28 pseudogene 7)
Gene: Processed pseudogene on chromosome 11 (82,689,559 to 82,689,768, forward strand). Ensembl gene ENSG00000227097.
Diseases named in the same sentence as RPS28P7 in open-access papers:
RPS28P7 is named in the same sentence as 2 diseases in open-access papers, as found by Europe PMC text mining. Sharing a sentence is not in itself a finding about the gene and the disease. The quoted sentences say what the papers report.
schizophrenia (1 paper, 2024). A major psychotic disorder characterized by abnormalities in the perception or expression of reality. "From total 66 DEGs, we identified 11 (16%) as pseudogenes, which comprised two main groups: mitochondrial pseudogenes increased in females (MTND1P23, MTCO1P12, MTCO1P40, and MTND2P28) and ribosomal pseudogenes increased in male schizophrenia patients (RPS4XP22, RPS16P4, and RPS28P7)." (PMID 39068467, 2024).
RPS28P7 also shares sentences with these, for which no sentence is quoted: Pancreatic Cancer (1 paper).